ZNF215 (zinc finger protein 215)
Description:
May be involved in transcriptional regulation.
Synonyms: BAZ-2; BAZ2; ZKSCAN11; ZSCAN43
Tractability: PROTAC: ubiquitination databases record sites on it.
Gene: Protein-coding gene on chromosome 11 (6,926,373 to 7,001,004, forward strand). Ensembl gene ENSG00000149054.
Subcellular location: Nucleus
Subcellular location (Human Protein Atlas): Nucleoplasm; Vesicles
Pathways (Reactome):
Gene expression (Transcription): Generic Transcription Pathway
Gene Ontology:
Molecular function: DNA-binding transcription factor activity; DNA-binding transcription factor activity, RNA polymerase II-specific; RNA polymerase II cis-regulatory region sequence-specific DNA binding; identical protein binding
Biological process: regulation of transcription by RNA polymerase II; regulation of DNA-templated transcription
Cellular component: nucleus
Genetic constraint (gnomAD): Loss-of-function variants: 23 observed, 27.89 expected, observed/expected ratio (o/e) 0.82, 90% interval 0.59 to 1.17. The upper end of that interval is the gene's LOEUF score, 1.17, which puts it in group 5 of 6, group 1 being the genes least tolerant of losing a copy. Missense variants: 635 observed, 606.74 expected, observed/expected ratio (o/e) 1.05, 90% interval 0.98 to 1.12. Synonymous variants: 201 observed, 206.86 expected, observed/expected ratio (o/e) 0.97, 90% interval 0.87 to 1.09.
Homologues: Orthologues: chimpanzee ZNF215 (98% identical), pig ZNF215 (66% identical), rabbit ZNF215 (66% identical). Paralogues in human: ZNF397 (26% identical), ZSCAN30 (25% identical), ZSCAN12 (25% identical), ZKSCAN1 (24% identical), ZKSCAN3 (24% identical), ZKSCAN4 (24% identical), ZSCAN22 (24% identical), ZKSCAN8 (23% identical), ZNF394 (23% identical), ZNF263 (23% identical), ZSCAN21 (23% identical), ZNF449 (22% identical), and 18 more.
Diseases named in the same sentence as ZNF215 in open-access papers:
ZNF215 is named in the same sentence as 7 diseases in open-access papers, as found by Europe PMC text mining. Sharing a sentence is not in itself a finding about the gene and the disease. The quoted sentences say what the papers report.
Beckwith-Wiedemann syndrome (2 papers, 2010 to 2021). Beckwith-Wiedemann syndrome (BWS) is a genetic disorder characterized by overgrowth, tumor predisposition and congenital malformations. "This region also harbors ZNF215, an imprinted gene associated with growth and body conformation traits in Holstein cattle and Beckwith-Wiedemann syndrome in humans, a genetic disorder characterized by growth abnormalities." (PMID 33633776, 2021).
acute myeloid leukemia (1 paper, 2023). Acute myeloid leukemia (AML) is a group of neoplasms arising from precursor cells committed to the myeloid cell-line differentiation. "Furthermore, the ZNF215 gene can be used as a diagnostic and prognostic biomarker for basal-like breast cancer and acute myeloid leukemia." (PMID 37260411, 2023).
cancer (3 papers, 2009 to 2023). A tumor composed of atypical neoplastic, often pleomorphic cells that invade other tissues. "S. saccharolyticus promotes cancer cell metastasis by regulating the expression level of the ZNF215 gene." (PMID 37260411, 2023). "To further explore the mechanism underlying the observed associations, we used three human gastric cell lines to verify the effect of the interaction between S. saccharolyticus and the ZNF215 gene on the metastasis of cancer cells." (PMID 37260411, 2023). "By comparing group 1 and group 6, we could verify the correlation among S. saccharolyticus, cancer cell metastasis, and the expression of ZNF215." (PMID 37260411, 2023). "By comparing group 4 and group 5, the correlation between the decreased expression level of the ZNF215 gene and the distal metastasis of cancer cells could be verified." (PMID 37260411, 2023). "By comparing group 2 and group 3, the results showed that S. saccharolyticus could further promote cancer cell metastasis by regulating the expression level of ZNF215." (PMID 37260411, 2023).
tumor (2 papers, 2009 to 2024). "In most cases (37/43 genes), methylation was more frequent in cell lines than primary tumours, however for 6 genes this pattern was reversed (ZNF215: 21% and 42% respectively, DAPK1: 4% and 39%, EPHA3 13% and 32%, SMARCB1: 8% and 27%, EPS8 4% and 21% and MCM2: 0% and 21%)." (PMID 19493342, 2009).
ZNF215 also shares sentences with these, for which no sentence is quoted: genetic disorder (2 papers); breast carcinoma (1); gastric cancer (1).